CCL22 (C-C motif chemokine ligand 22)
Diseases named in the same sentence as CCL22 in open-access papers (continued):
Sharing a sentence is not in itself a finding about the gene and the disease.
colon cancer (17 papers, 2012 to 2024). "High expression of CD1B and CCL22 was associated with longer OS for colon cancer patients." (PMID 34497681, 2021). "CCL22-specific T cells can recognize and kill CCL22-expressing breast and colon cancer cells, as well as lysed acute myeloid leukemia cells in a CCL22 concentration–dependent manner." (PMID 36175673, 2023). "The addition of anti-CCL22 neutralizing antibody in the medium or knockdown of CCL22 in miR-34a-/- colon tumor organoids reduced Th17 migration back to the wild-type level." (PMID 30543324, 2018). "(J) Chemotaxis assay showing knockdown of CCL22 in colon tumor organoid cells or neutralization of CCL22 with anti-CCL22 antibody suppresses Th17 cell migration to colon tumor organoid conditioned medium." (PMID 30543324, 2018). "Here, significantly increased tissue concentrations of the CCR4-ligand CCL22 were also found in colonic tumors, and probably contribute to recruitment of CCR4+ cells." (PMID 22319577, 2012). "It has confirmed that high expression of CCL22 is related to a better prognosis in patients with colon cancer, and CCL22 as a prognostic DEG is used to construct a cellular senescence-related risk model in colon cancer." (PMID 36925638, 2023). "CCR4 and its ligands CCL17 and CCL22 have been shown to mediate stimulatory signals for angiogenesis and tumor growth, and CCR4 blockade was associated with reduced tumor invasion and metastasis and better prognosis in some human cancer types such as hepatoma and colon cancer." (PMID 37124725, 2023). "The expression of M2-like macrophage markers Arg1, MRC1 and IL-10, CCL17, and CCL22 were down-regulated, and the expression of M1-like macrophage markers iNOS, IL-12, and TNFa were induced by cetuximab in modeled TAMs, treated with CM of colon cancer cells in vitro." (PMID 34209679, 2021). "Single cell RNA-sequencing revealed in vivo tumor cell-intrinsic CCL17 and CCL22 expression combined with expression from infiltrating classical resident and migratory dendritic cells in a CT26 colon cancer mouse tumor engineered to express LMP1." (PMID 35025968, 2022). "However, the relationship between CCL22 and colon cancer was unknown." (PMID 35664768, 2022). "IRG signature of AXIN2, CCL22, CLEC10A, CRIP2, RUNX3, and TRPM5 is a reliable prognostic predictor for colon cancer patients." (PMID 33401247, 2020). "Treatment with conditioned medium of colon cancer cells increased macrophage expression of the M2-related markers arginase-1 (Arg1), CCL17, CCL22, IL-10 and IL-4." (PMID 27683110, 2016). "Furthermore, qRT-PCR experimental results further confirmed that compared with normal colon epithelial cells, the expression levels of CCL22, CXCL1, CXCL8, and CXCL11 were upregulated in colon cancer cells." (PMID 38791448, 2024).
glioma (17 papers, 2015 to 2025). A benign or malignant brain and spinal cord tumor that arises from glial cells (astrocytes, oligodendrocytes, ependymal cells). "For example, the level of serum macrophage-derived CCL22 is associated with glioma risk and survival period." (PMID 35805111, 2022). "Another study proved that the levels of serum macrophage-derived CCL22 are associated with glioma risk and survival period." (PMID 31842422, 2019). "Our results indicating that VEGF, beta-Catenin and CCL22 levels increase glioma risk are consistent with previous post diagnostic and experimental literature." (PMID 28594935, 2017). "Further clarification is needed regarding whether glioma-related production of CCL22 is related to levels of CCL22 in peripheral blood, as well as whether glioma-derived CCL22 is also associated with disease prognosis." (PMID 26217588, 2015). "Particularly, CCL22 (C-C motif chemokine ligand 22) is found in many types of human cancers and has lower expression levels in gliomas cases than in controls." (PMID 35800363, 2022). "Differentiated Tregs recruited into tumor region were mediated by chemokines MCP-1 and CCL22 secreted by glioma cells." (PMID 34211978, 2021). "Cytokines related to glioma risk (P ≤ .05) more than 10 years before diagnosis are sIL10RB, VEGF, beta-Catenin and CCL22." (PMID 28594935, 2017). "In particular, gliomas are known to produce CC chemokine ligand 22 (CCL22), which serves as a potent chemotactic factor for leukocytes expressing CCL22 receptor CC chemokine receptor 4 (CCR4)." (PMID 26217588, 2015). "Specifically, production chemokine CCL22 by glioma cells is believed to play a key role in recruiting and trafficking peripheral nTregs into the glioma milieu, a subject that is discussed in more depth in subsequent sections of this review in Ref." (PMID 26217588, 2015). "Due to the efficient glucose uptake and glycolysis, glucose was deprived in the hypoxic lesions by glioma cells, resulting in Tregs relying on fatty acids for mitochondrial metabolism and migrating to glioma tissues in response to CCL22 in a HIF-1α-dependent manner." (PMID 34211978, 2021). "HIF-2α inhibition may regulate the recruitment of Tregs to the glioma site through a reduction of Treg-attracting chemokines such as CCL17, CCL22, and CCL18 or a re-polarization of the pro-tumoral macrophages secreting these factors." (PMID 40095115, 2025). "In gliomas with high CASZ1 expression, we found a restricted infiltration level but upregulated chemokines, including CXCL16, CCL22, CCL25, and CXCL2, which could attract DCs and T cells." (PMID 36276925, 2022). "CCL22, IL2RB and IRF4 were found to be competitive endogenous RNAs whose expression intensity may predict the prognosis of glioma patients." (PMID 32667033, 2020). "We found three positive (VEGF, beta-Catenin and C-C motif chemokine 22 (CCL22)) and two negative (LIF, sIL10RB) associations between five prediagnostic serum cytokines and the subsequent risk of glioma." (PMID 28594935, 2017). "IL-10 and CCL-22 were secreted from macrophages at lower levels when the cells were exposed to ACF-pretreated hypoxia-stimulated glioma supernatants than from cells exposed to non-ACF-pretreated hypoxia-stimulated-U87/U251 supernatants." (PMID 27602954, 2016). "Glioma-infiltrating Tregs express particularly high levels of CCR4 compared to other tumor-infiltrating lymphocytes, and several in vitro migration studies have demonstrated the ability of glioma-derived CCL22 to induce Treg chemotaxis." (PMID 26217588, 2015). "Similar to gliomas, several non-CNS tumors, including ovarian, breast, prostate, gastric, esophageal, as well as Hodgkin lymphoma tumor cells can also elaborate CCL22 to help recruit Tregs into the tumor microenvironment." (PMID 26217588, 2015). "Additionally, in a serum analysis of 1,208 patients with glioma, one group recently reported that lower serum levels of CCL22 were a negative prognostic indictor for overall survival." (PMID 26217588, 2015).
glioma (continued). "Whether CCL22 and/or CCL2 are significant Treg chemotactic factors in vivo is still a matter of contention; however, it is evident that other soluble factors within the glioma microenvironment also contribute to Treg chemotaxis, and these factors remain to be identified." (PMID 26217588, 2015).
hepatocellular carcinoma (17 papers, 2013 to 2025). A malignant tumor that arises from hepatocytes. "A previous study clarifies that M2 macrophage-derived CCL22 can motivate the migration ability of hepatocellular carcinoma and EMT behavior." (PMID 34874224, 2021). "In this study, we demonstrated that dysregulation of p65/miR‐23a/CCL22 axis contributed to Tregs recruitment and hepatocellular carcinoma growth." (PMID 31769216, 2020). "The migration of MHCC-97H cells (Human hepatoma cells) toward M2 supernatants was significantly reduced when the THP-1-derived M2 macrophages were pretreated with fucoidan for 24 h or CCL22 neutralizing Abs were added to the coculture system." (PMID 27775051, 2016). "It was deduced that the axis of p65/miR‐23a/CCL22 was presented in the hepatocellular carcinoma cells and might drive the tumor progression by recruiting Tregs, particularly when HBV infection was involved." (PMID 31769216, 2020). "For instance, Tregs, which abundantly express CCR4, CCR8 and CCR10, were directed to hepatocellular carcinoma (HCC) sites, where their corresponding ligands, CCL22 and CCL28, were present, affecting the treatment outcome by evading the immune system." (PMID 40852716, 2025). "TGF-β, the potent inducer of tumor progression and metastasis, can augment CCL22 production by reducing the level of its upstream antagonist miR-34a in hepatocellular carcinoma (HCC)." (PMID 32425930, 2020). "TAMs were reported to induce tumor progress via the CCR4-CCL17 axis in hepatocellular cancer, the CCR4-CCL22 axis in prostate cancer, and CCL22 in esophageal squamous-cell carcinoma." (PMID 37371612, 2023). "Chemokines secreted by hepatoma cells, such as CCL5, CCL22, and CCL28, increase the infiltration of those Tregs, leading to the impaired activity of antigen-presenting cells (APCs) and immune cells in TME." (PMID 35965575, 2022). "MiR‐23a was inversely correlated with CCL22 and Foxp3 in HBV+ hepatocellular carcinoma tissues." (PMID 31769216, 2020). "The upstream regulators modulating CCL22 in hepatocellular carcinoma (HCC) were not clearly understood." (PMID 31769216, 2020). "In hepatocellular carcinoma (HCC), increased TGF-β signaling, which is associated with persistent hepatitis B virus (HBV) infection, results in suppression of miR-34a and subsequently enhances the production of the chemokine CCL22, which promotes the recruitment of regulatory T cells." (PMID 29958433, 2018). "The previous study in hepatocellular carcinoma provided direct evidence that TGF-β could suppress the expression of miR-34a, resulting in the enhanced production of CCL22 and recruitment of Tregs." (PMID 25647263, 2015). "Persistent HBV in hepatocellular carcinoma (HCC) tissue maintained TGF-β activity, which repressed miR-34a expression, which in turn increased both CCL22 and recruitment of Tregs." (PMID 37671150, 2023). "In hepatocellular carcinoma (HCC), LPS promotes cell survival, proliferation, invasion, and production of pro-inflammatory mediators, including TNF-α, iNOS, IL-1β, IL-6, CCL-2, CCL-22, vimentin, and epidermal growth factor receptor (EGFR), through the induction of TLR4 signaling." (PMID 40444051, 2025).
vitiligo (16 papers, 2014 to 2025). Generalized well circumscribed patches of leukoderma that are generally distributed over symmetric body locations and is due to autoimmune destruction of melanocytes. "Many studies reported that Treg deficiency and impaired skin migration, due to reduced CCL22 expression, are hallmarks of vitiligo pathogenesis." (PMID 40933988, 2025). "The lack of Tregs in vitiligo is caused by a decrease in the Treg homing receptor CCL22 in the skin of vitiligo patients." (PMID 35884944, 2022). "In addition, there is an association between reduced expression of CCL22, a skin-homing chemokine, and Treg infiltration in vitiligo skin, suggesting impaired migration of Tregs to the skin in vitiligo patients." (PMID 33717132, 2021). "The number of Tregs and molecules that support their function, such as homing receptor C-C Motif Chemokine Ligand 22 (CCL22), were found diminished in vitiligo lesions." (PMID 36902341, 2023). "Alternative to Treg expansion, elevating the recruitment of Treg to the epidermis through gene‐gun‐treatment‐induced CCL22 overexpression also delayed vitiligo progression." (PMID 33200838, 2021). "Here, we found another targeted treatment strategy in vitiligo treatment, as PD-L1 fusion protein treatment had a similar treatment effect as CCL22 and simvastatin." (PMID 29371688, 2018). "Strategies to enhance Treg skin homing, such as cutaneous overexpression of the chemokine CCL22, have shown promise in promoting local immune regulation and could be leveraged for vitiligo therapy." (PMID 40933988, 2025). "Such local T-reg deficiency might be overcome by recruiting T-regs to the skin by means of topical administration of CCL22 (C-C motif chemokine ligand 22) DNA, as demonstrated in vitiligo-prone mice." (PMID 39063004, 2024). "Interestingly, by introducing CCL22 into the skin it was possible to cease depigmentation in a mouse model of vitiligo." (PMID 35884944, 2022). "In addition, CCL22 inhibits depigmentation and promotes Treg cell migration in vitiligo." (PMID 34077992, 2021). "In contrast to the findings in vitiligo, Th2 signaling was prominent as well, with consistent upregulation of CCL13, CCL17, CCL22, and CX3CL1." (PMID 40969764, 2025). "According to the studies included in the meta-analysis, treating vitiligo mouse models with antigen-specific CAR Tregs, PD-L1 fusion peptides, and CCL22 DNA reverses depigmentation by increasing the number of Tregs and FOXP3 expression in the skin." (PMID 36164321, 2022). "Chemokine ligand-receptor pairs that guide the migration of Tregs include CCL1 and CCR8, CCL21 and CCR7, and CCL22 with its receptor CCR4, while studies on vitiligo skin samples only revealed a significant reduction in CCL22 expression." (PMID 35096274, 2022). "CCL22 activates the migration and activity of Tregs in vitiligo, which has been shown to be decreased in vitiligo skin, whereas no changes were found for CCR4, CCR5, CCR8 and cutaneous lymphocyte antigen (CLA)." (PMID 39274437, 2024). "Studies have shown that various cytokines including interferon-γ (IFN-γ), tumor necrosis factor α (TNFα) and chemokine (C-C motif) ligand 22 (CCL22) are differentially expressed in the lesional skin and serum of vitiligo patients and health controls, indicating their roles in vitiligo." (PMID 24681574, 2014). "Several studies demonstrate reduced levels of CCL5/CCR4, CCL22, CCL21, and CCR6 in vitiligo skin, which could explain the failure of circulating Tregs to localize to the skin, thus suggesting that the modulating expression of these chemokines may be potential therapeutic targets in vitiligo." (PMID 36675037, 2023).
COVID-19 (14 papers, 2021 to 2025). A disease caused by infection with severe acute respiratory syndrome coronavirus 2. "In the current work, we investigate existing views on MDC/CCL22 dynamics in association with various pathologies, including respiratory diseases and, specifically, COVID-19." (PMID 37685890, 2023). "Furthermore, lower nasopharyngeal CCL22 mRNA expression is associated with severe COVID-19." (PMID 36482706, 2023). "CCL22 is a biomarker of severe COVID-19; CCL22 controls immunity by promoting the communication of regulatory T cells to dendritic cells, which is essential for recruiting Th2 cells in the respiratory tissues." (PMID 38543303, 2024). "On the other hand, lower expression of CCL22 mRNA was observed in nasopharyngeal specimens from severe COVID-19 patients when compared to mild patients." (PMID 36482706, 2023). "In summary, ADA appears to be a better biomarker to differentiate between infected and uninfected patients, while CCL22 has the potential in stratifying the severity of COVID-19." (PMID 36482706, 2023). "We analysed the serial MPO, ADA, CCL22, TNFα, and IL-6 mRNA expression in nasopharyngeal specimens of 154 COVID-19 and 163 control hospitalized patients in the fifth wave of COVID-19 in Hong Kong." (PMID 36482706, 2023). "In summary, the present study demonstrates the increase in nasopharyngeal MPO, ADA, CCL22, TNFα, and IL-6 mRNA expression in COVID-19 patients." (PMID 36482706, 2023). "Further research is necessary to fully comprehend the complex interactions between MDC/CCL22, its producer cells, immune regulation in COVID-19, and coagulation factors." (PMID 37685890, 2023). "Summary of research on COVID-19 focusing on the levels of MDC/CCL22 in the blood plasma of patients in the acute phase and those who have recovered." (PMID 37685890, 2023). "One such chemokine is MDC/CCL22, a promising molecule that can serve as the potential marker of COVID-19 severity." (PMID 37685890, 2023). "Patients with severe COVID-19 had higher IL-10 and lower CCL22 compared to the mild or moderate group." (PMID 35958594, 2022). "In the multiplex cytokine assays, plasma levels of Th2-related soluble factors such as IL-4, IL-5, IL-13, and CCL22 were comparable between the patient with COVID-19 mRNA vaccine-related myopericarditis and healthy controls." (PMID 35251049, 2022). "Patients with severe COVID-19 had higher IL-10 and lower macrophage-derived chemokine (MDC, CCL22) compared to the mild or moderate group (P<0.05)." (PMID 35958594, 2022). "In our study, we noticed an interesting trend concerning CCL22/MDC in COVID-19 pathogenesis: namely, a decrease in the concentrations of this chemokine in comparison with healthy donors." (PMID 36012323, 2022). "Additionally, we present our explanations for the observed decrease in MDC/CCL22 concentrations in COVID-19." (PMID 37685890, 2023). "Conversely, and regardless of vaccination status, antibodies to CCL19, CCL8, CCL13, CCL16, CXCL7 and CX3CL1 significantly increased, those to CXCL17 remained generally stable and those to CCL22 followed variable kinetics at month 12 compared with month 6 in the COVID-19 convalescents." (PMID 36879067, 2023). "Long-term depletion of MDC/CCL22 concentrations in blood plasma of acute COVID-19 patients and convalescents may explain the relatively greater severity of COVID-19 in comparison with other respiratory viral infections." (PMID 37685890, 2023). "This concurs with previous findings that impairment of dendritic cells could be persistent up to 7 months from the diagnosis of COVID-19, making CCL22 a promising and durable marker for severe COVID-19." (PMID 36482706, 2023). "Thus, the chemokine antibody signature that distinguished healthy controls from COVID-19 convalescents (autoantibodies to CCL19, CCL22 and CXCL17) was different from the signature associated with COVID-19 severity (autoantibodies to CXCL5, CXCL8 and CCL25)." (PMID 36879067, 2023).